MIR4671 (microRNA 4671)
Synonyms: hsa-mir-4671
Gene: MicroRNA gene on chromosome 1 (234,306,467 to 234,306,539, forward strand). Ensembl gene ENSG00000264377.
Homologues: Orthologues: chimpanzee MIR4671 (100% identical).